IL1B (interleukin 1 beta)
Diseases named in the same sentence as IL1B in open-access papers (continued):
Sharing a sentence is not in itself a finding about the gene and the disease.
infection (continued). "Temporal analysis of inflammatory cytokine induction revealed that while SARS-CoV-2 infection of parental THP1/PMA cells did not result in induction of pro-inflammatory responses, infection of CD169+ THP1/PMA cells led to rapid induction of IL-6, TNFα, IL-1β, and IFNλ1 mRNA expression." (PMID 36279285, 2022). "Notably, we found that the levels of IL‐1β and TNF‐α in the serum and lung were substantially reduced at 12 h, and even at 16 h, 24 h, and 32 h post PmCQ2 infection by melatonin injection." (PMID 35184395, 2022). "Correlation of post-infection sampling time points with plasma cytokine levels from both cohorts showed no clear time-dependent decrease of IL-1β, IL-6, and TNF plasma levels in participants with PASC." (PMID 35732153, 2022). "In terms of cytokine release, we observed increased release of IL-8 from dPLBs after infection with opsonized A. fumigatus conidia, but not IL-1β, consistent with our observations of human PMNs." (PMID 34986319, 2022). "Moreover, the experimental infection resulted in increased LZM, as well as enhanced levels of inflammatory factors, including IL-1β, IL-6, TNF-α and IL-10 in serum, indicating activation of inflammatory response following E. coli inoculation." (PMID 36198724, 2022). "Similarly, the expression of the proinflammatory cytokines IL-1β, IL-6, and TNF-α was induced by H7N9 infection, but decreased in response to pdmH1N1 infection." (PMID 35269402, 2022). "During infection, NLRP3 is the primary producer of IL-1β and IL-18." (PMID 35626718, 2022). "Here we found that the expression of proinflammatory cytokines IL-1β and IL-6 was increased 48 h after infection, but not at later times." (PMID 36068296, 2022). "Here, we observed that the production of inflammatory TNF-α and IL-1β and anti-inflammatory IL-10 was not changed following infection with Δnmo2 and Δnmo5 in contrast to infection with the wild-type strain." (PMID 35887491, 2022). "While infection with strain Nine Mile I rendered the cells partially refractory to re-stimulation with E. coli lipopolysaccharide, Cb30/14 exerted a selective suppressive effect which was restricted to IL-6 and TNF-α and spared IL-1β." (PMID 36558755, 2022). "Importantly, we found that WT, Gbp1–/–, Gbp2–/–, Gbp3–/–, Gbp5–/–, and Aim2–/– BMDMs all released similar levels of IL-1β, IL-18 and LDH in response to infection with F. novicida in the presence of E. coli LPS." (PMID 35906252, 2022). "Interestingly, IFI16 recognized the genome of HSV-1 in infected cells prior to viral gene expression, but later in infection, HSV-1 targeted IFI16 for degradation, thereby inhibiting maturation of IL-1β." (PMID 36298668, 2022). "The infection of A549 and SK-OV-3 with HAdV26 induced changes in the expression of the IL-6, IL-8, IL-1β, and TNF-α genes; namely the expression of all four genes was increased in HAdV26-infected A549 cells, while HAdV26 infection resulted in increased expression of IL-6 and TNF-α in SK-OV-3 cells." (PMID 35458402, 2022). "HIF-1 has been shown to induce il1b and inos expression and increase nitric oxide (NO) production, and il1b and inos mRNA and the nitrite concentration were increased in BMM at different times after infection with BCG." (PMID 36121152, 2022). "In contrast, administration of acetic acid, for which levels were also increased upon infection with A. fumigatus, did not play a protective role and increased the levels of the inflammatory cytokines IL-1β and TNF-α." (PMID 34445184, 2021). "This double-deletion mutant did not exhibit any IL-1β secretion in BMDM upon infection, demonstrating that the increase in IL-1β secretion in Δmag1 parasites is indeed dependent on GRA15." (PMID 34006649, 2021). "IL‐1β, IL‐6, and TNF‐α are important for acute phase protein production and fever induction, while IL‐12, IL‐18, and IFN‐γ recruit neutrophils to the site of infection and elicit a T helper type 1 (Th1) adaptive immune response." (PMID 33970545, 2021).
infection (continued). "IL-1β did not increase during infection in microglia-depleted BSCs and was significantly lower at baseline than non-depleted BSCs, demonstrating that inflammasome activation and IL-1β release depend on microglia in a model of HSE." (PMID 33524073, 2021). "Infection at early stage did not induce a significant change in cytokines production and IL-1β and TNF-α expression levels measured in hippocampal/thalamic were comparable to ME7 mice treated with saline." (PMID 35058740, 2021). "IL-1α, IL-1β, MIP-1α, and tumor necrosis factor alpha (TNF-α) were reduced in both IAV- and mock-infected animals at 24 h pbi during infection with each SGD mutant compared to their levels during infection with WT D39 (P < 0.05), except for D39ΔpurD in mock-infected animals (P > 0.05)." (PMID 33875471, 2021). "To further test the anti-IL-1β effect, we explored IL-1β response in the absence of prior infection." (PMID 34092247, 2021). "At 24 h post-infection, serum levels of IL-6, IL-17A, TNF-α, and IFN-γ were greatly reduced in IL-38-treated group, CCL2 and CXCL10 decreased at day 4, IL-1β and CCL-5 decreased on day 7 in the IL-38-treated group compared with group without IL-38 treatment." (PMID 33414457, 2021). "Besides, W-KP2 infection significantly induced the up-regulation of pro-inflammatory cytokines, such as IL-1β, IL-6, TNF-α, and IFN-γ in mice at 72 h after infection." (PMID 33968007, 2021). "In addition, after SFTSV infection, IL-1β release significantly decreased in NLRP3 knockout THP-1 macrophages than wild type cells, but it was higher than mock infection in NLRP3 knockout macrophages." (PMID 33708197, 2021). "Interestingly, Mmass infection significantly increased the TNF, IL-1β, and CXCL2 levels in BMDMs after 18 h of infection." (PMID 33473145, 2021). "In contrast, chronic CS exposure (>2 weeks) results in exaggerated cytokine responses (TNF-α, IFN-y, IL-6, IL-12, IL-23, IL-1, IL-5, IL-10, KC, MIP-1a, IL-17, IL-1B) with infection compared to non-smoking infected controls." (PMID 34959590, 2021). "Analysis of relative expression over the 5 time points of infection revealed significant upregulation of TNFα, IL1β and IL2 at 28dpi, compared to the brain of non-infected PBS controls." (PMID 34899715, 2021). "Furthermore, Dnmt3bfl/flSpCcre and control mice showed similar CXCL5, CCL20, IL-1β and TNF-α BALF levels upon infection with PAK." (PMID 33793661, 2021). "GSK872 also did not impact cell death and appeared to impact TNF and IL-1β expression for infections with PA14." (PMID 33664232, 2021). "In particular, TLR3 might act via IRF3, producing interleukin (IL)-1α, IL-1β, IL-4, IL-6, and IFN-α and IFN-β, during the first 24 h post-infection." (PMID 34576716, 2021). "Whole-blood infection with C. albicans in either an active or inactive state induced a strong and comparable secretion of monocyte-derived cytokines (TNF-α, IL-1β and IL-6), whereas only low cytokine levels could be detected in mock-infected blood." (PMID 34103589, 2021). "For example, infection-induced levels of TNF-α, IL-1β, and IL-17A were higher in the sera of pregnant mice than in the sera of virgin control mice, which parallels their increased bacterial burden, whereas the anti-inflammatory cytokine IL-10 peaked to higher levels in virgin than in pregnant mice." (PMID 33622714, 2021). "However, 2 days post-infection with V. anguillarum, 2 % of ARA increased the expression of il-1β and cox2 genes and 4 % increased il-10 expression." (PMID 36420498, 2021). "Morphological changes in bMECs, including swelling, shrinkage, necrosis and hematoxylin and eosin staining of cytoplasm, were apparent 4 to 8 h after infection with K. pneumoniae, but each bacteriophage significantly suppressed damage and decreased TNF-α and IL-1β concentrations." (PMID 33468111, 2021).
infection (continued). "Taken together, these results demonstrate that during infection with the ΔpknF mutant, XO plays an important role in the generation of ROS that in turn is responsible for activation of NLRP3 inflammasome and increased production of IL-1β." (PMID 34324582, 2021). "The role for IL-1β in the defense against Ft is not yet well understood; however, IL-1β in the BALF of C57BL/6J mice i.n. infected with a lethal dose of LVS is higher at day 3 post-infection than at day 6 post-infection." (PMID 34202420, 2021). "The expression of IL-1β, IL-6, IL-8, IL-18, TNF-α, MMP-9, RANKL, TLR-2, TLR-4, TLR-6, thymic stromal lymphopoietin (TSLP), and ICAM-1 was evaluated by qPCR at 2 and 24 h after infection." (PMID 33802988, 2021). "The host response to infection could be regulated by TGFβ1 with the help of a cytokine storm and the presence of TNF, IL-1β, and IL-6." (PMID 33693030, 2021). "Among these cytokines, IL-1β levels in the toxigenic and non-toxigenic groups rapidly increased at 6 h post infection, but no significant change was observed at the following sampling time point." (PMID 33665221, 2021). "Collectively, the infection outcomes of mice of the three genotypes were not consistent with the IL-1β expression levels but consistent with the neutrophil chemoattractant Cxcl1." (PMID 34011393, 2021). "After the infection with GTP viruses (GTPV) and PPR viruses (PPRV), cytokines such as TNF-α, IL-1β, IL-6, IL-10, IFN-α, and IFN-β might regulate their replication in vitro." (PMID 33827620, 2021). "Infection of Casp-1 inhibitor-treated cells and NOD-, LRR- and pyrin domain-containing 3 (NLRP3)-knockdown cells indicated that NLRP3 is essential for FMDV-induced IL-1β secretion." (PMID 35062226, 2021). "Thus, in the context of infection, TLR and IL-1β signaling contributes to IgMFt production, but during immunization Myd88-mediated signaling appears dispensable." (PMID 34449811, 2021). "At 6 and 12 h post-infection, the mRNA expression levels of caspase-3, caspase-1, GSDMD, RIPK3, MLKL, NLRP3, IL-1β, and IL-18 were upregulated in RAW264.7 macrophages infected with either E. faecalis CA1, CA2, or OG1RF strains compared to the levels in the control group." (PMID 34513732, 2021). "The suppression of TNF-α and IL-1β production undoubtedly promoted the ability of Lm NTSN to evade the direct bacteria-killing of macrophages, thus contributing to its survival during the early stage of infection." (PMID 35223532, 2021). "Thus, the high levels of pro-IL-1β secretion observed after stimulation with the MAC can be relevant both in the context of sterile inflammation and during infection." (PMID 34650553, 2021). "The expression of cytokines (IL-1β and TNF-α) as a vital part of the immune system is modulated by infection or inflammation, so assessing their expression levels may help explain the mechanisms of specific contaminants’ toxicity." (PMID 34062969, 2021). "However, we did note a trend (p < 0.1) for interactions between infection and LB supplementation for the expression, of ARG1, TLR3, IL1B, and CTLA4, with the infection-induced expression of these genes being attenuated to some extent by LB." (PMID 35069576, 2021). "Infection by genetically diverse clinical strains of M. tuberculosis revealed an upregulation of NFKB1 and NFKB2 transcriptional factors that lead to the transcription of IL1β, while IL18 was slightly down-regulated at 48 h infection by East-Asian and Euro-American lineages." (PMID 34502407, 2021). "With the increased infection time, IL-1β and TNF levels did not consistently increase at 6 h postinfection compared to 3 h, whereas IL-6 and IL-10 did." (PMID 33664232, 2021). "We found that inhibition of ERK1/2, serine proteases and cathepsin B, but not p38, NF-κB and PKC, resulted in significantly lower IL-1β release compared to DMSO treated cells after CFT073 infection at MOI 1 for 6h." (PMID 34944029, 2021).
infection (continued). "However, both probiotics increased the mRNA expression of IL-1β, INF-γ, IL-13, IL-17, and TGF-β in the jejunum at seven days post infection (day 28)." (PMID 34136557, 2021). "Interestingly, the in vitro infected primary PCPEC displayed a very strong cellular response during the infection with S. suis ST2, with a maximum of 134-fold up-regulation for IL1β." (PMID 33763387, 2021). "Brain fibrinogen was related to IL-1β (and IL-13 to a smaller extent) in early and intermediate stages of disease (BS0–II and III–IV) but the relationship was lost in end stage disease, or with infection." (PMID 33723589, 2021). "THP-1, THP-FAKi (THP-1 treated with FAK inhibitor) and THP-FAK+ (THP-1 overexpressing FAK) macrophages were infected with Mtb and culture supernatants were collected at 24 hours post-infection to quantify the levels of TNF-α, IL-1β and IL-10 using the solid-phase sandwich ELISA." (PMID 34745115, 2021). "Changes of cytokines IL‐1β, IL‐5, IL‐7, and IL‐12p40 within 6 hours after infection in the animal model were not significantly different between the two types of bacteria infected groups." (PMID 34725873, 2021). "In this case, EVs containing virus particles and exosomal proteins activate multiple molecules, initiate a productive infection of CD4+ T cells, and upregulate the expression of proinflammatory cytokines, such as interferon (IFN)-γ, tumor necrosis factor (TNF), interleukin (IL)-1β, and CCL5." (PMID 34988085, 2021). "Although MT3 exerted disparate effects on caspase-11 activation in gram-positive and gram-negative infections, caspase-1 and IL-1β activation was suppressed by MT3 in both infection settings." (PMID 34867993, 2021). "IL-1β neutralization during acute in vivo infection restored expansion in the Δmag1 parasites but did not have an effect on parasite expansion in WT parasites." (PMID 34006649, 2021). "Our panel showed positive IFN-β, IL-12A, IL-1β and TNF-α immunostaining in the tissues of squirrel monkeys, demonstrating a similar profile in the nervous tissues of the newborns in G1, who were born after maternal infection." (PMID 33731800, 2021). "Moreover, infection of B.1.1.7 and B.1.351 resulted in significant elevation of several key inflammatory cytokines in K18-hACE2 mice, including TNF-α (lung), IL-1β (lung), IL-6 (lung and liver), IL-13 (liver), IFN-α (liver) and IFN-β (liver)." (PMID 34772941, 2021). "On Day 4 post-infection there were no or very low detectable levels of systemic IL-6, IL-1α or IL-1β in the Group 3.2 animals." (PMID 34452519, 2021). "In contrast, infection of wild-type BMDM with SCHU S4 resulted in no measurable levels of IL-1β and in the presence of IFN-γ, low levels of IL-18, whereas no IL-18 was secreted in the absence of IFN-γ." (PMID 35004352, 2021). "In addition to live DSV, we found that heat killed DSV (autoclaved) also induced NICD, p21, and pro-IL-1β protein expression at MOI20, 7 hr post infection compared to control (p<0.05)." (PMID 34336718, 2021). "Collectively, these results suggest that IL‐1β exacerbates disease during severe IAV infection and that early IL‐1β inhibition from day 1 does not render mice more susceptible to infection." (PMID 33834544, 2021). "Bx795 abolished the induction of type-I/III IFNs, CXCL10, and TNF due to PVSRIPO infection; induction of IL-1β, IL-6, and IL-10 was not affected." (PMID 33767151, 2021). "While TNF-α and IL-1β were both produced during the early stages of infection, neither was dependent on TNC (P = 0.74 and P = 0.75, respectively)." (PMID 34319124, 2021). "While there were not significant effects of tributyrin supplementation on IL1B mRNA levels, there was a trend observed at 10 d PI for +BE groups to have higher expression regardless of infection status." (PMID 33652244, 2021).
infection (continued). "The mRNA expression of various inflammatory cytokines (Il-6, Tnf-α, Ifn-γ, and Ifn-β) and chemokines (Ccl2, Ccl4, Ccl12, Cxcl1, and Cxcl10), but not Il-1β, was elevated in the lungs at 2 dpi, in the early stage of infection." (PMID 34463644, 2021). "However, IL-1β and cleaved caspase-1 secretion stimulated by SFTSV infection or LPS/Nigericin were all inhibited by the inhibitor CY-09." (PMID 33708197, 2021). "In trachea, the IL-1β mRNA expression level in group IV showed no significant changes from day 1 to 5 post-infection." (PMID 34988139, 2021). "Moreover, virus mixed infection enhanced the mRNA expressions of TNF-α, IL-1β, IL-6, IL-10, IFN-α, and IFN-β by 2–170 times." (PMID 33827620, 2021). "Casp1/11 double knockout BMDMs failed to secrete IL-1β and undergo cell death during ΔpknF mutant infection in contrast to infection of wild-type BMDMs with ΔpknF mutant." (PMID 34324582, 2021). "Infection of bMECs with Prototheca spp., especially P. bovis, damaged mitochondria and promoted mtROS accumulation, which activated an inflammatory response through the NF-κB and NLRP3 inflammasome pathways and enhanced IL-1β production." (PMID 34895324, 2021). "Along with this observation, we also observed significantly lower levels of IL-6, IFN-γ, and CXCL-10 24 h post-infection, IL-17A and TNF-α 4 days post-infection, and IL-1β, CCL2 and CCL5 7 days post-infection in the lung of IL-38-treated mice, compared with mice without IL-38 administration." (PMID 33414457, 2021). "In this study, we found that vaccination-trained immune response produces heightened TNF-α, but not IL-6 and IL-1β, when encountered with the infection." (PMID 34544549, 2021). "Strikingly, infection with NTSNΔinlF triggered significantly higher production of cytokines IL-6 (p <0.05) and IL-1β (p <0.05) in the spleen; there was no obvious difference in TNF-α elicited by three Lm strains (p >0.05)." (PMID 35223532, 2021). "Cytokines (IL-1β, IL-12, TNF-α, and IFN-γ) were quantified in sera 15 days after infection." (PMID 34336720, 2021). "In contrast with these studies, we did not observe significant DCA-inhibiting effects on IL-1β, IL-10 and IL-6 secretion by Stm- or Mtb-infected human macrophages, possibly because infection alone already strongly skewed the cytokine response." (PMID 34552598, 2021). "Furthermore, we pretreated BMDMs with the Nlrp3 inhibitor (MCC950) and Caspase-1 inhibitor (Z-YVAD-FMK) prior to the infection with SS2, and we observed the expected significant inhibitions to the IL-1β release and cytotoxicity." (PMID 32922370, 2020). "Thus, we confirmed that the activation of Caspase-1/11 and Gsdmd was required for the SS2-induced IL-1β release and cytotoxicity in BMDMs ex vivo, and this activation contributes to mouse death and IL-1β release in response to the SS2 infection in vivo." (PMID 32922370, 2020). "The release of other known candidalysin-induced proteins, such as hBD2, hBD3, LL37, G-CSF, GM-CSF, IL-1α and IL-1β, do not appear to be affected by Apyrase during infection." (PMID 32178483, 2020). "In contrast, in additional analysis, we showed that infection with UT127 could induce the expression of genes such as TNF, IL1B, and PTGS2, which together induce activation of apoptosis in MoCT but not in MoTB." (PMID 32391286, 2020). "Cag A upraise the accumulation of cytokinesresponsible for the inflammation like interferon-γ, IL-6, IL1, IL10, IL8, IL1β, TNFα and IL-7.It activates NF-κB, Wnt/β-catenin, PI3K/Akt, Ras, ERK/MAPK, sonic hedgehog and STAT3 is disorganized with the infection of H. Pylori CagA+ strains." (PMID 32405173, 2020). "IL-1β, CXCL1, CXCL2, and CCL2 expression was significantly higher in the lungs of klotho KO mice infected with A. baumannii than in those of klotho WT mice at 1 day post-infection." (PMID 33329595, 2020).